INS (insulin)
Diseases named in the same sentence as INS in open-access papers (continued):
Sharing a sentence is not in itself a finding about the gene and the disease.
diabetes (continued). "In the obesity + diabetes group, leptin correlated with sICAM1 rho = 0.786, and sVCAM1 negatively with glycemia/insulin rho = −0.85." (PMID 32858998, 2020). "It is a transitory period that is marked by significant amount of endogenous insulin production by residual β cells following diabetes mellitus diagnosis and initiating the insulin therapy." (PMID 32215008, 2020). "We defined T1D as diabetes diagnosed <30 years of age, on insulin treatment from diagnosis and with a history of ketoacidosis." (PMID 32528078, 2020). "Effect of diabetes and insulin on body weight, water intake, food intake, glycemia, urine volume and urine glucose concentration." (PMID 32182246, 2020). "At present, diabetes is treated with oral antidiabetic medicines, such as sulfonylureas and thiazolidine, as well as insulin injection." (PMID 33281368, 2020). "They criticized the current negative perception of community members’ regarding patients with diabetes, thus they felt embarrassed injecting insulin in public." (PMID 32532266, 2020). "The main approach in treating and managing diabetes consists of multiple daily injections of insulin together with the continuous and accurate monitoring of BGLs in order to maintain their values within the normoglycemic range of 70–140 mg dL−1." (PMID 32325974, 2020). "Diabetes mellitus is a metabolic syndrome which results from inadequate insulin or impaired action of insulin." (PMID 33062013, 2020). "The variables collected are: the number of times pregnant, plasma glucose concentration a 2 h in an oral glucose tolerance test, diastolic blood pressure, triceps skin fold thickness, 2-h serum insulin, body mass index, age, and the diabetes pedigree function." (PMID 33195014, 2020). "Development of insulin resistance is a key step in the progression of metabolic syndrome, obesity, and diabetes, and it occurs when increasing levels of insulin are required to stimulate insulin-induced glucose uptake, particularly in myocytes and adipocytes." (PMID 33133017, 2020). "Diabetes mellitus is a metabolic disorder characterized by impaired insulin production and reduced insulin sensitivity." (PMID 33182646, 2020). "Since Japanese have a lower insulin secretory capacity than Caucasians, they are more likely to have diabetes." (PMID 33195702, 2020). "In conclusion, in our study, ucOC positively correlated with insulin secretion independently of BMI in Japanese individuals with diabetes." (PMID 32821293, 2020). "His mother and the mother’s brother also have diabetes (treated with diet and insulin, respectively)." (PMID 32910913, 2020). "Diabetes is a heterogeneous metabolic disorder that is characterized by the presence of hyperglycemia due to impairment of insulin secretion, defective insulin action, or both." (PMID 32554386, 2020). "The anti-inflammatory effect seems to be the mediator between MD and diabetes mellitus by improving insulin sensitivity via better endothelial function by increasing flow-mediated dilation and decreasing intercellular adhesion." (PMID 32354060, 2020). "He had been treated with oral anti-diabetic agents instead of insulin for 10 years until premixed insulin twice daily was started again due to poor diabetes control." (PMID 32982980, 2020). "The present study was aimed to evaluate the efficacy of injectable insulin on diabetes mellitus-related complications in comparison to orally encapsulated insulin nanoparticles." (PMID 32695298, 2020). "The median time between diabetes diagnosis and starting insulin therapy (which was the discriminative criteria of patients in the two groups) was 0 months in T1DM (range 0–4 months, IQR 0.0) and 48 months in LADA (range 6–396 months, IQR 56.3)." (PMID 33292447, 2020). "Fasting glucose, insulin, triglycerides, and glucose tolerance test were performed as a measure of diabetes in the CON and HFHC dams." (PMID 32987812, 2020).
diabetes (continued). "Diabetes mellitus (DM) is a group of heterogeneous metabolic diseases mainly characterized by a hyperglycemic condition, with a defect in insulin secretion or action." (PMID 32041110, 2020). "On the other hand, several diabetes therapies with insulin-lowering properties appear to be beneficial, particularly for patients with advanced PCa." (PMID 32932589, 2020). "Cyanidin also up-regulated the expression of the genes that have potential implications on insulin secretion, glucose homeostasis, and diabetes." (PMID 33255297, 2020). "In parallel with the reports from animal models of diabetes, recent studies with obese insulin-resistant humans showed that carnosine supplementation modestly attenuates insulin release and enhances the extrusion of reactive aldehydes in urine." (PMID 32977552, 2020). "There were 19 acromegaly patients with diabetes (28.8%), among which 2 patients were treated with insulin and 9 patients were treated with drugs." (PMID 33414826, 2020). "Among obesity- and diabetes-related factors, insulin and insulin-like growth factor 1 (IGF-1) were identified as negative regulators of 11β-HSD1 expression and subsequent eGC production in skin." (PMID 33260645, 2020). "Diabetes mellitus is characterized mainly by hyperglycaemia occurring due to defects in insulin secretion, insulin action, or both." (PMID 33299532, 2020). "There are several conditions in which insulin disturbance is pathologic: for example, diabetes mellitus (type 1 diabetes mellitus and type 2 diabetes mellitus), insulinoma, metabolic syndrome, and polycystic ovary syndrome." (PMID 32142224, 2020). "Insulin has been available for the treatment of diabetes for almost a century, and the variety of insulin choices today represents many years of discovery and innovation." (PMID 32396624, 2020). "They showed that adipsin knockout mice developed exacerbated diabetes due to β-cell failure, and isolated islets from these mice exhibited decreased insulin secretion." (PMID 32079203, 2020). "In another Hong Kong Diabetes Registry10, 7.9% type 2 diabetes patients were receiving dietary treatment only, 52.9% were taking OHAs and 39.2% were receiving insulin therapy." (PMID 31161658, 2020). "In the present time, it is known that the progressive defect in insulin production due to insulin resistance represents 90–95% of all individuals with diabetes mellitus type 2 (DM2)." (PMID 32079175, 2020). "Similar GSMR models were also implemented (diabetes: β = 1.13, P-value = 1.16E-4; glucose: β = 0.246, P-value = 3.87E-04; insulin: β = 1.47, P-value = 4.72E-10)." (PMID 32612641, 2020). "This can be explained by the need for special storage of some medicines (eg, recombinant human erythropoietin for kidney disease or insulin for diabetes)." (PMID 32716892, 2020). "T1DM adolescents with six years of diabetes duration and insulin treatment showed poor glycemic control and alterations in some plasma, urine, and cardiovascular parameters." (PMID 32708413, 2020). "The fact that the questionnaire isnot specific to a chronic disease as such, but that it allows substitution of termssuch as asthma or diabetes, medical treatment by inhalers or insulin when it iscompleted facilitates its use." (PMID 32022154, 2020). "Examples include recombinant human insulin for the treatment of diabetes, erythropoietin for renal failure‐induced anemia and interferon for viral hepatitis." (PMID 31123862, 2020). "Insulin is the standard treatment of choice in the treatment of immunotherapy mediated type 1 diabetes mellitus." (PMID 33123445, 2020). "The high percentage of pioglitazone use, which increases insulin sensitivity, is a characteristic diabetes treatment for patients with Werner syndrome." (PMID 33373317, 2020). "Diabetes, a series of chronic metabolic disorders characterized by hyperglycemia, is the result of defects in insulin secretion, insulin action, or both." (PMID 33202751, 2020).
diabetes (continued). "Dysfunction of β-cells leads to a decrease in insulin secretion, which plays an important role in the development of diabetes." (PMID 32184820, 2020). "Hypoglycemia, defined as a blood glucose level <70 mg/dL (3.9 mmol/L), is the most common and highly feared acute complication of diabetes mellitus, particularly in patients with insulin therapy." (PMID 32256577, 2020). "As Akt activation is known to exert anti-apoptotic effects and it is inhibited in glomerular endothelial cells by diabetes, we characterised the direct effect of glucose levels on insulin signalling and Akt activation in podocytes." (PMID 32238837, 2020). "The role of the A2bAR in insulin and glucose sensitivity has been extensively studied in mouse models of obesity and diabetes and appears to play an active role in maintaining glucose homeostasis." (PMID 33050467, 2020). "Diabetes mellitus are a group of metabolic disorders characterized by hyperglycemia, resulting from defects in insulin secretion, insulin sensitivity, or both." (PMID 32528413, 2020). "For ultimate treatment to cure T2DM, association of diabetes with immune components provides a strong basis for immunotherapies and vaccines developments that could stimulate the immune cells to minimize the insulin resistance and initiate gluconeogenesis through an insulin independent route." (PMID 32703184, 2020). "The impaired insulin signaling forms a tight link between obesity and type 2 diabetes mellitus, making adipocytes a suitable model for the investigation of the disease’s pathophysiology." (PMID 33092038, 2020). "Nanoformulations were also found to be efficacious against common metabolic syndrome, such as diabetes mellitus to deliver insulin and oral hypoglycaemic agents." (PMID 32210082, 2020). "Following the use of high-dose corticosteroids, most of the patients required insulin due to their known or hidden diabetes, and the insulin requirement was increased in the methylprednisolone group, especially in diabetic and overweight patients." (PMID 32943404, 2020). "While there was a nearly equal split of oral anti-diabetes drugs (OADs)-only and Insulin treatment in LHLH’s discharge pharmacotherapy, insulin treatment dominated SMH’s." (PMID 32267843, 2020). "Diabetes mellitus (DM) is caused by insulin deficiency as shown by insufficient production of insulin (type-1 diabetes mellitus, T1DM) or insulin resistance (type-2 diabetes mellitus, T2DM) and, thus, leads to chronic hyperglycemia." (PMID 32393384, 2020). "Three participants known to have diabetes were on insulin therapy; a further 18.5% were found to be hyperglycaemic (11.2% IFG, 5.9% IGT and 1.4% type 2 DM)." (PMID 33033015, 2020). "Diabetes mellitus (DM) is a group of metabolic disorders described by hyperglycemia that occurs due to defects such as insulin secretion, decreased sensitivity of insulin receptors, or both." (PMID 33110487, 2020). "Mitochondrial dysfunction has been linked to a 60% decrease in muscle insulin sensitivity in healthy, young, lean insulin-resistant offspring of parents with diabetes." (PMID 33046063, 2020). "Nowadays, synthetic insulin or insulin analogues, which have modified primary sequences compared with human insulin, have become the standard of diabetes care due to their more favourable pharmacokinetic profile." (PMID 33006670, 2020). "Most of these studies reported that participants with longer diabetes duration were more likely to start insulin early compared to those with short duration." (PMID 32318630, 2020). "Type 2 diabetes mellitus (T2DM), responsible for 90–95% of diabetes cases, is characterized by hyperglycemia due to a combination of insulin resistance and inadequate compensatory insulin secretion in β cells." (PMID 32960890, 2020). "Here we show that miR-181b, a key regulator for endothelial function, beta cell function, peripheral insulin sensitivity, and NFκB signaling, participates in the control of vascular TF activity in diabetes." (PMID 32066445, 2020).
diabetes (continued). "But this is not aspected since type 2 diabetes abnormalities (such as reduced insulin secretion, increase of insulin resistance) start several years before that the diabetes clinical manifestations appears." (PMID 32132977, 2020). "In this section, results of experimental and clinical studies are described aiming at exploring the relationship between insulin signalling and its effect on PTs, on glucose excretion, and on renal glucose transporters, particularly in diabetes." (PMID 32377524, 2020). "Insulin resistance is the main reason behind the development of diabetes and resulted in a decrease in the secretion of insulin from β cell of pancreas." (PMID 32815547, 2020). "This mini-review summarizes the recent insights into the beneficial effects of vitamin K and its possible mechanism of action on insulin sensitivity and glycemic status, thereby suppressing the progression of diabetes mellitus." (PMID 32824773, 2020). "In diabetes, reduced insulin action on skeletal muscle, the liver, and adipose tissue causes hyperglycemia and impairs the normally rapid postprandial decline of serum FFA levels." (PMID 33150239, 2020). "Antidiabetic agents including oral antidiabetic agents and insulin were given to 3314 (35.7%) patients who accounted for 81.3% of the patients with diabetes." (PMID 32703284, 2020). "Shorter duration of diabetes and higher initial fasting plasma insulin levels suggestive of better β-cell function are predictors for higher chance for remission in response to weight loss." (PMID 32597475, 2020). "Diabetes mellitus is a metabolic disease which is characterized as hyperglycemia resulted from defects in insulin action and/or insulin secretion." (PMID 33193101, 2020). "Pancreatic β-cells, a type of endocrine cell that secretes insulin and regulates blood sugar, play a central role in the pathogenesis of diabetes." (PMID 32659127, 2020). "Diabetes can inhibit insulin/IRS1 signalling in mesangial and glomerular endothelial cells, probably through the protein kinase C (PKC) β2 pathway." (PMID 32238837, 2020). "Diabetes mellitus (DM) is a major public health problem that is determined with impaired carbohydrate metabolism, protein, and fat due to unstable insulin secretion, insulin resistance secretion, or both." (PMID 32013917, 2020). "Type 2 diabetes (T2D) comprises more than 90% of all diabetes cases and is characterized by decreased insulin sensitivity in target organs like muscle and adipose tissue as well as reduced pancreatic insulin secretion." (PMID 32276427, 2020). "Diabetes mellitus (DM) is characterized by disruption in glucose homeostasis and defects in insulin action on many target tissues including liver, muscle, pancreas, and adipose." (PMID 32498358, 2020). "STZ is a DNA alkylating agent, and its intraperitoneal or intravenous injection caused marked infiltration of inflammatory cells and reduced insulin secretion leading to diabetes." (PMID 32104545, 2020). "This has initiated new research exploring the opportunities of bioelectronic medicine for improving glucose control in people with diabetes, including regulation of gastric emptying, insulin sensitivity, and secretion of pancreatic hormones." (PMID 32467827, 2020). "Diabetes results from defective insulin secretion, insulin resistance, or excessive glucagon secretion, and eventually causes severe complications by disrupting the metabolism of carbohydrates, proteins, and lipids." (PMID 32977701, 2020). "The Epidemiology of Diabetes Interventions and Complications study revealed that the incidence of obesity in T1D patients has significantly increased due to widespread intense insulin treatment following Diabetes Control and Complications Trial." (PMID 31434460, 2020). "Most patients managed their diabetes with oral glycemic agents (49%) at the time of their lymphoma diagnosis and 26% were using insulin or insulin in combination with oral glycemic agents; 28% of patients managed diabetes with diet alone." (PMID 33437504, 2020).
diabetes (continued). "Streptozotocin (STZ) causes pancreatic beta (β)-cell destruction and, subsequently, compromises insulin production, leading to an insulin-dependent diabetes mellitus." (PMID 33287432, 2020). "In both DPT-1 studies, insulin secretion before the diagnosis of diabetes was evaluated by the assessment of the C-peptide response during mixed-meal, oral glucose, and intravenous glucose-tolerance testing." (PMID 32204344, 2020). "Diabetes is characterized by exceedingly high serum glucose levels and is often connected to dysregulation of insulin signaling." (PMID 33316971, 2020). "Previous studies reported that MAFA was a transcription factor binding RIPE3b, a conserved enhancer element that regulated pancreatic beta cell-specific expression of the insulin gene, which was involved in Insulinomatosis and Diabetes Mellitus." (PMID 32680461, 2020). "Rapid glucose responsive insulin release into the blood circulation is desirable in the treatment of diabetes." (PMID 33202992, 2020). "Diabetes mellitus is a long-term condition that occurs when there are high glucose levels in a person’s blood because their body cannot produce any or enough insulin or cannot effectively use the insulin it produces." (PMID 32927754, 2020). "PA flower has a potential role in the management of diabetes as complementary and alternative therapy, due to its antioxidant, anti-inflammatory, hypolipidemic, hypoglycemic and insulin secretagogue effects." (PMID 32967670, 2020). "Stem cells show significant therapeutic potential in patients with diabetes, due to their immunomodulatory properties and ability to regenerate into insulin-producing cells (IPCs)." (PMID 32010488, 2020). "The enrolled groups were homogenous in all, except for diabetes-related biochemical parameters (glucose and insulin concentration, HbA1C)." (PMID 33062144, 2020). "In one study, patients with AD and type 2 diabetes mellitus have been treated with either oral antidiabetic drugs or a combination of insulin with other diabetes medications." (PMID 32380758, 2020). "Adipose tissue also enriched the Adipocytokine signaling pathway, pointing towards the role of adipose tissue in insulin secretion defects of diabetes measured as HOMA-β." (PMID 32294959, 2020). "Studies in mice treated with PTX experimentally induced by SZT diabetes showed a reduction in blood glucose levels, increased plasma insulin concentration, and inhibition of T-cell proliferation." (PMID 33153226, 2020). "7.43% of patients with diabetes from 4 mg group required insulin and 5.46% of patients with diabetes from 8 mg group required insulin." (PMID 33047085, 2020). "Studied groups were similar in mean age, diabetes duration, metabolic control, and daily insulin requirement." (PMID 32793113, 2020). "Type 2 diabetes mellitus (T2DM), which accounts for less than 90% of diabetes cases, involves insulin resistance (IR) in peripheral tissues and increased levels of blood glucose, because of overnutrition with an insulin secretion defect." (PMID 32733635, 2020). "As diabetes progresses, it becomes increasingly difficult to treat, as the capacity to endogenously produce insulin diminishes and life-threatening complications arise." (PMID 32929089, 2020). "It is possible that insulin and c-peptide resistance occur simultaneously in this type of diabetes; however, taking into consideration that insulin treatment is sufficient to neutralize blood glucose levels, this scenario appears unlikely." (PMID 33419247, 2020). "DEPS-R is a 16-item questionnaire for general and diabetes-specific DEB assessment, including weight loss, food restriction, insulin measure and vomiting." (PMID 33287458, 2020). "For example, of the 59 (20.4%) patients with diabetes treated with insulin, 29 (10.03%) were also on additional oral diabetes agents." (PMID 32385343, 2020).